FGF4 (fibroblast growth factor 4)
Diseases named in the same sentence as FGF4 in open-access papers (continued):
Sharing a sentence is not in itself a finding about the gene and the disease.
cancer (continued). "In ovarian cancer, the evidence of induction of cancer stem cells is limited, with a few reports indicating the role of CAF derived fibroblast growth factor 4 and IL-6 in inducing cancer stem cells." (PMID 30380628, 2018). "KLb affects FGF4 signaling pathway, phosphorylation of ERK1/2 and FRS2, resulting in enhancement of cell proliferation or inhibition of cancer cell apoptosis." (PMID 29731962, 2018). "Several known cancer-related genes, such as CCND1, FGF4, FGF3, and CTTN, have been mapped to the 11q13 chromosome region." (PMID 24930674, 2014). "The probable target genes that are amplified and/or overexpressed in different cancers have been reported to include CCND1, FGF4, PPFIA1, CTTN and ORAOV1." (PMID 22920630, 2012). "Therefore, FGF-2 and FGF-4, abundant in stromal tissues, enhance EMT of invasive cancer cells, and sustain aggressive phenotypes." (PMID 36140527, 2022). "Thus, epithelial cells undergoing EMT and aggressive cancer cells become sensitive to FGF-2 and FGF-4, likely through upregulated FGFR1-IIIc expression." (PMID 36140527, 2022). "Later on, the enhanced expression of the SASP factors CXCL12, HGF, MMPs and TGFβ in irradiated fibroblasts was reported to increase EMT and invasiveness of cancer cells, and enhanced expression of the SASP factors EGF, FGF-4, GM-CSF, IGF-1,2, IGFBP-2,4,6 induced chemoradioresistance in cancer cells." (PMID 32384619, 2020). "KLγ also might affect FGF4 signaling pathway, ERK1/2 pathway and EMT, resulting in cancer prognosis." (PMID 29731962, 2018). "Positive FGF4 expression was observed in 11 of 13 patients (84.6%) with advanced stage carcinomas (TNM stages III and IV), and in 27 of 47 patients (57.4%) with early-stage carcinomas (TNM stages I and II)." (PMID 27677589, 2016). "However, the ORAOV1 gene was identified within chromosomal band 11q13, which includes several known cancer-related genes such as CCND1, FGF4, FGF3, and CTTN." (PMID 24930674, 2014). "In adults, FGF4 is produced only under pathological conditions by certain cancer cells, while HeLa cell line has been characterized as non-expressing FGF4." (PMID 20804557, 2010).
skeletal dysplasia (4 papers, 2020 to 2022). Any Mendelian diseases that affects growth and development of the skeleton. "Given the previous association of FGF4 retrogenes with skeletal dysplasia, FGF4L4 genotype was also compared to height at the withers in 24 Border Terriers using multiple linear regression." (PMID 32717834, 2020). "Consistent with the skeletal dysplasia phenotype common to both retrogenes, presence of 1 or 2 copies of either the CFA12 or CFA18 FGF4 retrogenes was also associated with “smaller” dogs (based on body weight)." (PMID 32793650, 2020). "Breeds carrying one FGF4 retrogene copy (CFA12 or CFA18) tend to have skeletal dysplasia with moderately short limbs, while those carrying both copies, such as Dachshunds, Corgis and Bassett Hounds, have the most severe form of disproportionate dwarfism." (PMID 32793650, 2020). "Notably, multiple recent FGF4 retrocopy insertions have also been reported in dogs, several of which are expressed and involved in skeletal dysplasias." (PMID 36047852, 2022).
bacterial infection (1 paper, 2021). "(B) Binding of individual phage clones to EF43.fgf4 cells was quantified by the counting of transducing units (TU) after host bacterial infection." (PMID 34060472, 2021).
lung (1 paper, 2016). "Finally, 60 human lung ADC samples and 21 sets of matched specimens (primary and metastatic foci in lymph nodes from one patient) were used to confirm the clinicopathologic significance of FGF4 and its correlation with E-cadherin, Vimentin and Orai1 expression." (PMID 27677589, 2016). "In the human lung ADC tissue samples, we observed higher levels of Orai1 expression in the FGF4 strong expression group than in the weak and negative expression groups." (PMID 27677589, 2016).
metabolic disorders (1 paper, 2021). "The potent anti-hyperglycemic and anti-inflammatory properties of FGF4 testify to its promising potential for use in the treatment of T2D and related metabolic disorders." (PMID 34907199, 2021).
FGF4 also shares sentences with these, for which no sentence is quoted: acral melanoma (1 paper); adrenal cancer (1); Alzheimer disease (1); autism (1); autoimmune hepatitis (1); bladder tumors (1); colorectal cancer (1); epilepsy (1); gastric tumors (1); gastrointestinal stromal tumor (1); Glucose intolerance (1); hidradenoma of the skin (1); Huntington disease (1); Hyperinsulinemia (1); influenza (1); Intellectual disability (1); ischemic disease (1); metastatic tumors (1); microcephaly (1); mucoepidermoid carcinoma of salivary glands (1); myopia (1); neuroblastoma (1); non-small cell lung carcinoma (1); oral squamous cell carcinoma (1); pancreatic adenocarcinoma (1); peripheral vascular disease (1); prostate carcinoma (1); renal fibrosis (1); sarcoma (1); type 2 diabetes (1).